PRAME (PRAME nuclear receptor transcriptional regulator)
Diseases named in the same sentence as PRAME in open-access papers (continued):
Sharing a sentence is not in itself a finding about the gene and the disease.
melanoma (continued). "Importantly, high PRAME levels were found to correlate with advanced stages of disease in melanoma, neuroblastoma, serous ovarian adenocarcinoma, and chronic myeloid leukaemia, and to constitute an independent prognostic factor of poor clinical outcome in breast cancer." (PMID 22912744, 2012). "Other significant correlations between melanoma immunohistochemical markers such as Melan-A, HMB45, S100 or PRAME and Breslow depth highlight their potential not only for diagnostic but also for prognostic purposes." (PMID 41155720, 2025). "Advanced imaging (MRI) and immunohistochemical analysis revealed the mass to be a superficial spreading melanoma expressing SOX10, PS100, Melan-A, HMB-45, and PRAME." (PMID 39862670, 2025). "Tumor cells from both modalities were highly similar, and key melanoma marker genes—including S100A1, MLANA, MCAM, and PRAME—were consistently highly expressed." (PMID 41446065, 2025). "The study included 46 paraffin-embedded melanoma samples, and the staining efficacy for markers such as Melan A, HMB-45, PRAME, and Ki-67 was assessed via both methods." (PMID 39930005, 2025). "We analyzed PRAME and Melan A expression regarding the nuclear PRAME expression pattern and pagetoid spread of melanocytes by immunohistochemical staining in SSM with prominent nests, nested melanoma, and dysplastic melanocytic nevi." (PMID 40941765, 2025). "Here, the expression of PRAME, SOX10, Melan-A, and HMB45 which are routinely used for melanoma diagnosis were evaluated." (PMID 40437181, 2025). "The original tumor cells exhibited diffuse positivity for PRAME and SOX10, while they were focally positive for Melan-A and very focally positive for HMB45, confirming the diagnosis of melanoma." (PMID 40437181, 2025). "By evaluating the IHC staining of commonly used markers in melanoma diagnosis and assessment—namely, Melan A, HMB-45, PRAME, and Ki-67 (The first two stain the cytoplasm, while the latter two stain the nucleus)." (PMID 39930005, 2025). "For this reason, we investigated the role of PRAME in differentiating between SSM with prominent nests, nested melanomas, and benign dysplastic melanocytic nevi." (PMID 40941765, 2025). "Furthermore, PRAME expression in basal cell carcinoma and Merkel cell carcinoma is a potential pitfall that could lead to a misdiagnosis of malignant melanoma, especially in small biopsies and when melanoma is clinically suspected." (PMID 38338862, 2024). "Other studies have shown that PRAME expression can be induced by 5-azaC treatment in AML and melanoma." (PMID 39091741, 2024). "Previous studies on high PRAME expression in SS, and reports on its interaction with EZH2 and RARs in melanoma and AML prompted us to analyze the expression of PRAME, EZH2, and the RAR genes in different soft-tissue sarcomas (STS)." (PMID 39550391, 2024). "Several proteins are commonly used as markers for melanoma in immunohistochemistry testing: S-100 protein, SOX-10, HMB- 45, PRAME, and MART-1." (PMID 38748192, 2024). "These experiments confirmed variable levels of PRAME-pHLA complexes between cell lines; melanoma MEL624 cells, which have high PRAME expression genotype, had abundant complexes on the plasma membrane, whereas glioblastoma CHP212 cells did not." (PMID 39659431, 2024). "In seminomas, PRAME expression correlated with TET1, but in melanomas and synovial sarcomas, it correlated with both DNMTs and DNMT3A, respectively." (PMID 38541782, 2024). "In melanoma and AML, the high expression of PRAME is generally indicative of a more aggressive phenotype and is considered an adverse prognostic factor." (PMID 38338862, 2024). "One study identified peptides derived from a CTA called PRAME (preferentially expressed antigen in melanoma) in OS and EWS and showed that PRAME-specific T cells can induce tumor regression." (PMID 37038005, 2023).
melanoma (continued). "For example, PRAME expression is promoted by MZF-1, which leads to the enhancement of colony-forming capability of melanoma cells, and is inhibited by miR-211 in malignant melanoma cells." (PMID 38132219, 2023). "However, the prognostic role of PRAME in melanoma patients is unknown." (PMID 34359765, 2021). "C1QB, CXCL9, CXCL10, DFNA5 (GSDME), FCGR1B, and PRAME were increased in melanoma, and SCGB1D2 was decreased in melanoma, compared to dysplastic nevi or nevi that progressed to melanoma." (PMID 35008167, 2021). "Investigating ATRA response mechanisms, we focused on PRAME, recently reported as a dominant repressor of RAR signaling in AML, and SOX9, a transcription factor significantly down-regulated in melanoma specimens." (PMID 29484133, 2018). "The melanoma case with absent PRAME expression exhibited diffuse S-100 and Melan-A expression, with HMB-45 expression present in both superficial and deep components." (PMID 41153267, 2025). "Our data suggest that, especially in cases without pronounced pagetoid spread, PRAME is not a suitable marker to diagnose nested melanoma, as none of the cases in this group exhibited diffuse PRAME positivity." (PMID 40941765, 2025). "PRAME shows a diffuse nuclear expression in most cases of melanoma (> 75%), while benign nevi exhibit weak or absent staining." (PMID 40509563, 2025). "Preferentially expressed antigen in melanoma (PRAME) is highly expressed in malignant melanoma but not in benign melanocytic proliferations." (PMID 40984891, 2025). "Diffuse PRAME positivity (staining of >75% of epidermal or >75% of dermal melanocytes; 4+) was found in 6 of 10 (60%) SSM with prominent nests and in 5 of 26 (19%) nested melanomas." (PMID 40941765, 2025). "Of the non-diagnostically challenging melanomas, 100% had copy number alterations and 77.8% were positive for PRAME." (PMID 40227827, 2025). "In our cohort, PRAME expression was observed in 39 out of 40 primary melanoma cases (97.5%), with one SSM case showing no expression." (PMID 41153267, 2025). "They found diffuse PRAME staining in 58.6% of cases, which did not serve as a marker for distinguishing metastasizing from non-metastasizing thin melanomas." (PMID 40941765, 2025). "Notably, cancers such as melanoma, AML, and ovarian cancer harbor uniquely expressed genes, including well-characterized immunotherapy targets like PRAME, MPO and MUC16." (PMID 40672284, 2025). "PRAME (preferentially expressed antigen in melanoma) immunohistochemistry consistently shows patchy and weak staining in BIMT and serves as a reassuring tool to distinguish BIMT from melanoma." (PMID 39268598, 2025). "Immunostains were strongly positive for SOX10 and PRAME (preferentially expressed antigen of melanoma); while negative for BRAF, VE1, NRAS, Q61L, and DOG1." (PMID 38933829, 2024). "For example, PRAME positivity is only present in approximately 35% of desmoplastic melanomas; we observed that 5hmC levels are largely retained in desmoplastic melanoma (data not shown)." (PMID 39091741, 2024). "It is known that PRAME expression in benign nevi is absent or weakly stained, whereas melanomas often have a strong PRAME expression." (PMID 38338862, 2024). "Analysis of TCGA and GTEx databases confirmed a negative relationship between TET2 and PRAME mRNA expression in melanoma." (PMID 39091741, 2024). "Also, PRAME IHC positively correlated with both DNMTs and DNMT3A in melanomas and synovial sarcomas, respectively." (PMID 38541782, 2024). "In this report, we show that PRAME is equally expressed in melanoma and lung tumors, independent of immune cell infiltration." (PMID 39659431, 2024). "A cohort of primary melanoma samples from 14 patients were examined using cyclic immunofluorescence (CyCIF) imaging and antibodies against SOX10 (melanocytes), CK14 and panCK (epidermal keratinocytes), PRAME, TET2 and 5-hmC." (PMID 39091741, 2024).
melanoma (continued). "Specifically, most cases of malignant melanoma exhibited positive immunoreactivity to PRAME; in contrast, most benign melanocytic nevi did not." (PMID 38132219, 2023). "For instance, a study comparing nodal nevi and melanoma metastases demonstrated that PRAME was expressed in 0% of the nevi and in 100% of the lymph node metastases." (PMID 37958863, 2023). "Additional functions of PRAME are suggested as reduced PRAME expression interferes with melanoma cell proliferation even in the absence of RA." (PMID 37173882, 2023). "PRAME was comprehensively expressed in MBM (median: 79.8%, range: 119.4–72.8%) with one exception (Pat10) that showed no PRAME expression and was classified as primary central nervous system (CNS) melanoma." (PMID 36435874, 2022). "When in situ and nondesmoplastic invasive melanoma components were present, PRAME expression was seen in both." (PMID 35328098, 2022). "As the expression of PRAME has not yet been studied in rhabdoid primary melanomas, we analyzed its expression in four primary melanomas with rhabdoid differentiation." (PMID 35645230, 2022). "Recently, p16 (mostly positive for NN) and PRAME (mostly negative for NN) have been introduced in the differential diagnosis to SN metastases of melanoma." (PMID 35059868, 2022). "All nodal nevi (30/30) were negative for PRAME, whereas all melanoma metastases (15/15) were diffusely positive for PRAME IHC." (PMID 35328098, 2022). "PRAME is an antigen that is predominantly expressed in melanomas with a low expression in non-tumor tissue." (PMID 35185883, 2022). "PReferentially expressed Antigen in MElanoma (PRAME) belongs to the group of cancer testis antigens (CTA) and its eponymous expression in melanomas may provide an immunohistochemical aid in the diagnosis of melanocytic lesions." (PMID 34359765, 2021). "Preferentially expressed antigen in melanoma (PRAME) is a cancer-testis antigen that is not normally produced by healthy human tissues but is expressed in different types of cancer." (PMID 34195690, 2021). "Non-diffuse PRAME expression by no means excludes a thin melanoma, as this staining pattern was observed in almost half of our studied melanomas." (PMID 34359765, 2021). "PRAME expression is not specific to melanoma but is also found in many other solid cancers as well as lymphomas and leukemias." (PMID 34359765, 2021). "The authors reported that the TCR mimic required tumor cells to induce expression of the immunoproteasome in order to correctly process the PRA300–309 peptide, as demonstrated by the lack of Pr20 binding and ADCC in several HLA-A2+ PRAME+ melanoma cell lines." (PMID 31311081, 2019). "This list included several oncogenes, namely MIR544A, MIR146B, FAM83A (also known as tumor antigen BJ‐TSA‐9), the cancer‐germline genes PBK (PDZ binding kinase) and PRAME (preferentially expressed antigen in melanoma), and GCKR that, with PRAME, is a downstream target of the BCR‐ABL protein." (PMID 29575763, 2018). "While it was not possible to detect PRAME-specific responses against the K562 HLA-A2+ cells or the 518A2 melanoma cells using the standard reporter, the CD2+CD226+ J76 PRAME TPR were stimulated by endogenously processed PRAME antigen expressed by these cells." (PMID 29707134, 2018). "PRAME was reported to repress retinoic acid signaling in melanoma cell lines, but this was not confirmed for breast cancer or leukaemia cases." (PMID 22912744, 2012). "PRAME mRNA is found frequently in advanced stages of malignancies such as melanoma, neuroblastoma and breast cancer, though not in the earlier stages of these diseases." (PMID 20799951, 2010). "In particular, tumors without pagetoid spread and with absent PRAME expression may in fact represent atypical or dysplastic melanocytic nevi rather than true melanomas." (PMID 40941765, 2025).
melanoma (continued). "Immunohistochemical markers such as PRAME and p16 may further aid classification; PRAME is highly specific for melanoma and is uniformly negative in benign nodal nevi but positive (>50% tumor cells) in metastatic melanoma." (PMID 41294657, 2025). "The absence of established molecular drivers associated with melanoma such as BRAF V600E mutations, along with the lack of PRAME staining expression by immunohistochemistry, a marker that is often positive in melanoma, can help confirm a benign diagnosis in NCH." (PMID 40265343, 2025). "It stained entirely negative for PRAME, which is unusual for a diagnosis of melanoma." (PMID 39420989, 2024). "Twenty-six percent (26.09%) of the melanomas showed diffuse PRAME staining in over 76% of the tumor cells (4+), and 34.78% of the melanomas showed PRAME expression in over 51% of the tumor cells (3+ or 4+), while 8% were entirely negative for PRAME." (PMID 39335694, 2024). "In a melanoma tumor, for example, some cells may express PRAME on the surface while other cells do not." (PMID 39451258, 2024). "Therefore, in the setting of metastatic disease, the diagnosis of melanoma should not solely rely on PRAME expression and should be confirmed by additional immunohistochemical or molecular analysis." (PMID 37958863, 2023). "To date, only one study compared superficial DN with melanomas by a manual score, revealing PRAME expression in only 1/35 DN (2.9%), while an early-stage melanoma could not entirely be excluded in this single case." (PMID 37047361, 2023). "In 7 cases (5.5%) of desmoplastic melanoma, PRAME was 1+ positive and/or completely negative." (PMID 36140597, 2022). "PRAME could also be expressed by some normal tissues and nonmelanocytic tumors, suggesting as caution should be adopted to use PRAME as a “pan-melanoma” marker for the differential diagnosis with other malignant tumors." (PMID 34508017, 2022). "Also, Preferentially expressed Antigen in Melanoma (PRAME), a tumor-associated antigen isolated by autologous T cells in a melanoma patient, was reported to be overexpressed in malignant melanomas rather than benign melanocytic lesions." (PMID 35484605, 2022). "PRAME expression is not a prognostic biomarker in melanomas ≤1.0 mm." (PMID 34359765, 2021). "The fact that the only SDN with diffuse PRAME staining was also the only case in which an early invasive melanoma could not be excluded histologically (SAMPUS) shows that diffuse PRAME expression correlates well with histological criteria for malignancy." (PMID 34359765, 2021). "Additionally, MAGE-3 was found to be expressed in melanoma but not in normal melanocytes while PRAME was determined to be an adequate marker for differentiating between melanoma cells and benign nevi." (PMID 23209909, 2012). "In our patient, the combination of benign morphologic features, PRAME negativity, HMB-45 loss, preserved p16 expression, and low proliferative index, together with a history of dysplastic nevus and no clinical or radiologic evidence of melanoma, supported the final diagnosis of nodal nevi." (PMID 40984891, 2025). "Finally, desmoplastic melanomas represent particular entities as they may appear deceivingly bland and usually lack expression of melanocytic markers such as HMB45, MelanA, tyrosinase, and PRAME but generally express S100 and SOX10." (PMID 37373134, 2023). "Interestingly though, both components stained for PRAME, suggesting this novel immunohistochemical marker may be helpful in dedifferentiated melanomas lacking expression of conventional melanocytic markers." (PMID 37373134, 2023). "Gene expression profiles of different stages of melanoma progression show that PRAME is expressed in primary melanoma, but not in healthy skin tissues or benign melanocytic lesions (nevi or moles), indicating that PRAME expression may be an event in melanocytic transformation." (PMID 34722301, 2021).
melanoma (continued). "While cytolytic activity was observed in melanoma cell lines, no activation of the T cell clones could be detected in the presence of ALL cell lines, which was postulated to be most probably linked to the lower expression of PRAME in the latter." (PMID 31311081, 2019). "PRAME has already been shown to be a prime candidate for such an immunotherapy, inducing strong immune responses in healthy volunteers and patients with AML, CML, ALL and melanoma, and could potentially form a polyvalent vaccine with other cancer-testis antigens." (PMID 20799951, 2010). "Cells expressing at least one melanoma lineage marker (MITF, PRAME or the melanocyte differentiation antigens) and negative for CD45 were considered melanoma cells." (PMID 39697983, 2024). "The case presented in this paper is only the second reported melanoma with angiosarcomatoid dedifferentiation highlighted by immunohistochemical expression of ERG and CD31, while lacking expression of MelanA and PRAME." (PMID 39001214, 2024). "PRAME was not expressed in brain-derived stromal cells and several MBM exhibited even higher levels than melanoma cell lines." (PMID 36435874, 2022). "Diffuse PRAME expression did not allow differentiation of MM from NMM (p = 0.81) and was not a prognostic biomarker in melanomas ≤1.0 mm." (PMID 34359765, 2021). "Out of the 17-gene classifiers that separate melanoma and non-melanoma, LINC0518 (Long Intergenic Non-Protein Coding RNA 518) and PRAME (preferentially expressed antigen in melanoma) were one of the best performing gene pairs in identifying melanoma." (PMID 31418068, 2019). "While the majority of MIS cases (12/19) had a PRAME+/5hmC− phenotype similar to primary and metastatic melanomas, two MIS cases were PRAME negative with high 5hmC, while other MIS cases (5/19) exhibited variable PRAME positivity in combination with clearly detectable but reduced 5hmC staining." (PMID 39091741, 2024). "All other markers tested were negative (pan-melanoma, HMB45, Melan A, keratin AE1/AE3, desmin, alpha smooth muscle actin, h-caldesmon, CD34, p16, CD117, DOG1, myogenin, CD10, estrogen receptor (ER), progesterone receptor (PR), PAX8, WT1, synaptophysin, chromogranin A, CD99 and PRAME))." (PMID 39196362, 2024).